NPM1 (nucleophosmin 1)
Diseases named in the same sentence as NPM1 in open-access papers (continued):
Sharing a sentence is not in itself a finding about the gene and the disease.
acute myeloid leukemia (continued). "Previous studies reveal an unexpected tendency for amyloid aggregation in specific regions of the C‐terminal domain (CTD) of nucleophosmin 1 (NPM1), a nucleolar chaperone involved in acute myeloid leukemia (AML)." (PMID 40400267, 2025). "Nucleophosmin 1(NPM1) is an abundant human protein endowed with many functions where whose dysregulation leads to various cancers and mutations are relevant in acute myeloid leukemia (AML)." (PMID 40400267, 2025). "Leveraging an engineered AsCas12a protein variant with high mismatch tolerance and broad PAM scope, CoHIT can use a single crRNA to detect multiple NPM1 gene c.863_864 4-bp insertions in acute myeloid leukemia (AML)." (PMID 38866774, 2024). "Mutations in nucleophosmin 1 (NPM1), FMS-like tyrosine kinase 3 (FLT3) and CCAAT/enhancer-binding protein α (CEBPA) contribute to risk stratification of cytogenetically normal acute myeloid leukemia (CN-AML)." (PMID 39767827, 2024). "Nucleophosmin 1 (NPM1) is commonly mutated in myelodysplastic syndrome (MDS) and acute myeloid leukemia." (PMID 39103576, 2024). "Studies have demonstrated that acute myeloid leukemia (AML) and NPM1 mutations are related." (PMID 38662949, 2024). "Nucleophosmin 1 mutations, occurring almost exclusively within exon 12 of the gene, occur in approximately one-third of adults with acute myeloid leukemia, and in more than 50% of NK-AML." (PMID 37047003, 2023). "Patients with acute myeloid leukemia (AML) and nucleophosmin 1 gene mutations (NPM1mut) show a favorable prognosis with chemotherapy (CT) in the absence of negative prognostic genetic abnormalities." (PMID 37402862, 2023). "Mutations in NPM1, also known as nucleophosmin-1, B23, NO38, or numatrin, are seen in approximately one-third of patients with acute myeloid leukaemia (AML)." (PMID 36834572, 2023). "Previous studies have primarily focused on the oncogenic role of NPM1 in acute myeloblastic leukaemia (AML)." (PMID 37251542, 2023). "NPM1 has been widely characterized for its oncogenic functions: it is often overexpressed in solid tumors and it is the most frequently mutated gene in acute myeloid leukemia (AML)." (PMID 37759327, 2023). "Acute myeloid leukemia MRD is evaluated using multiparameter flow cytometry and PCR-based testing for specific mutations (NPM1) or fusions (CBFB-MYH11, etc.)." (PMID 37700828, 2023). "Mutations in NPM1 are commonly associated with acute myeloid leukemia (AML)." (PMID 36743470, 2023). "To explore whether the abnormal m6A level exists in acute myeloid leukemia (AML) with NPM1 mutations, we first detected the m6A level of global RNAs." (PMID 35211409, 2022). "Instead, NPM1, which is involved in non-Hodgkin lymphoma and acute myelogenous leukemia, and CCTs (CCT4, CCT5, and CCT7) were up-regulated." (PMID 35464471, 2022). "In adult acute myeloid leukemia (AML), one-third of patients develop mutations in the NPM1 gene, resulting in abnormal cytoplasmic localization." (PMID 36280841, 2022). "NPM1 mutations account for around one third of patients with Acute Myeloid Leukemia (AML)." (PMID 35408798, 2022). "Leukemic cells derived from patients with acute myeloid leukemia (AML) carrying nucleo-phosmin (NPM1) secrete EVs enriched in miR-19a-3p." (PMID 36498469, 2022). "NPM1 is mutated in approximately one-third of newly diagnosed acute myeloid leukemia (AML) cases." (PMID 33654209, 2021). "Acute myeloid leukemia (AML) with mutated NPM1 accounts for one-third of newly diagnosed AML." (PMID 33654209, 2021). "Our study aims was molecular study of Nucleophosmin -1 gene in Acute Myeloid Leukemia in Kurdish population." (PMID 34795724, 2021). "In acute myeloid leukemia (AML), several NPM1 mutations have been reported, all resulting in cytoplasmic delocalization, but the putative biological and clinical significance of different variants are still debated." (PMID 34298672, 2021).
acute myeloid leukemia (continued). "In acute myeloid leukemia (AML), NPM1 gene is frequently mutated, leading to the aberrant translocation of the protein into cytoplasm." (PMID 34298672, 2021). "Although poorly characterized, the interplay between PARP1 and NPM1 was shown to be functional for treatment of acute myeloid leukemia." (PMID 33804735, 2021). "Classification of acute myeloid leukaemia patients’ NPM1 and FLT3-ITD genotypes (August 2020, Bloemfontein, Free State, South Africa)." (PMID 34230878, 2021). "Somatic mutations in exon 12 of the NPM1 gene is one of the most common genetic abnormalities in adult acute myeloid leukemia (AML), which is observed in 25-35% of AML patients and in 50-60% of patients with cytogenetically normal AML (CN-AML)." (PMID 33507703, 2021). "The mutations of NPM1 and FLT3-ITD represent the most frequent genetic aberration in acute myeloid leukemia." (PMID 33374216, 2020). "In a cohort of 50 adult acute myeloid leukemia (AML) patients, a high SOX11 expression was associated with FLT/ITD and NPM1 mutations and a shortened disease-free survival." (PMID 32029838, 2020). "In acute myeloid leukemia and some solid tumors, NPM1 gene overexpression is related to mitotic index and metastasis." (PMID 33142921, 2020). "Specifically, the acute myeloid leukemia (AML)-specific mutated NPM1 (mNPM1)-derived neoantigen CLAVEEVSL was delivered to DCs in the form of αCD40mNPM1 and αCD40.FlgmNPM1 antibody constructs, making this study the first to investigate mNPM1 in a DC vaccination context." (PMID 33281829, 2020). "This study aimed to investigate the correlation between GM-CSF gene expression and different molecular prognostic markers such as FLT3-ITD, NPM1 mutation A and CEBPA gene expression in Egyptian acute myeloid leukemia patients." (PMID 32711425, 2020). "Acute myeloid leukemia (AML) is a heterogeneous malignancy with the most common genomic alterations in NPM1, DNMT3A, and FLT3." (PMID 32754299, 2020). "The most frequent acquired molecular abnormalities and important prognostic indicators in patients with Acute Myeloid Leukaemia (AML) are fms-like tyrosine kinase-3 gene (FLT3) and nucleophosmin-1 (NPM1) mutations." (PMID 31244296, 2019). "Keeping in view its importance, molecular analysis for NPM1 and FLT3-ITD mutations should be included in the initial workup of all acute myeloid leukaemia patients." (PMID 30881390, 2019). "Moreover, in acute myeloid leukemia (AML)- associated mutations, the mutated NPM1 gene determines the formation of an aberrant NPM1 protein (NPM1c+) which re-localizes in the cytoplasm." (PMID 31307523, 2019). "Thus, we found further evidence of the pathogenetic role of NPM1, which is a protein highly implicated in the pathogenesis of acute myeloid leukemias (AML), in NPM-ALK + ALCL." (PMID 31390744, 2019). "This study aimed to evaluate DNMT3A exon 23 mutations and their prognostic impacts in the presence of NPM1 and FLT3 mutations in acute myeloid leukemia (AML) patients who underwent allogeneic hematopoietic stem cell transplantation (HSCT)." (PMID 29786546, 2018). "Our data strongly support the activation of autophagy as the cause of degradation of NPM1, NPMc+, and HEXIM1 in a subset of acute myelogenous leukemias." (PMID 27732946, 2016). "The aim of this clinical trial was to evaluate the impact of all-trans retinoic acid (ATRA) in combination with chemotherapy and to assess the NPM1 status as biomarker for ATRA therapy in younger adult patients (18–60 years) with acute myeloid leukemia (AML)." (PMID 27696203, 2016). "Included were DNMT3A R882 and NPM1 W288, which occur in 14.9 and 25.6 % of acute myeloid leukemia (LAML) patients, respectively and have been shown important in LAML oncogenesis." (PMID 27356755, 2016). "In contrast, in a study on acute myelogenous leukemia, a mutant NPM1 counterpart (NPMc+) was aberrantly localized in the cytoplasm of leukemic blasts." (PMID 25779011, 2015).
acute myeloid leukemia (continued). "In fact, NPM1 is the most frequently mutated gene in adult acute myeloid leukemia (AML)." (PMID 26091065, 2015). "Notably, NPM1 has been identified as the most frequently mutated gene in acute myeloid leukemia (AML) patients, accounting for approximately 30% of cases." (PMID 25849651, 2015). "We present a unique case of a patient who initially presented with acute myeloid leukemia (AML) with a normal karyotype and FLT3-ITD and NPM1 mutations." (PMID 26798525, 2015). "De novo acute myeloid leukemia (AML) with concurrent DNMT3A, FLT3 and NPM1 mutations (AMLDNMT3A/FLT3/NPM1) has been suggested to represent a unique AML subset on the basis of integrative genomic analysis, but the clinical features of such patients have not been characterized systematically." (PMID 25281355, 2014). "We show that NPM1 regulates TLS by protecting polη from proteasomal degradation, and that a deficiency in NPM1 as well as expression of the acute myeloid leukaemia (AML)-related NPM1c+ mutation results in decreased polη levels and defective TLS." (PMID 25421715, 2014). "Significance of a polymorphic nucleotide T deletion (rs34351976) in the 3’UTR of NPM1 was studied in acute myeloid leukemia (AML)." (PMID 25421940, 2014). "NPM1 is one of the most frequently mutated genes in acute myeloid leukemia (AML)." (PMID 24202322, 2013). "The prognostic implication of immunophenotyping in acute myeloid leukemia (AML) patients with NPM1 mutation remains unclear." (PMID 23496932, 2013). "Wang et al48 linked TET1 expression to M0/M1 morphology and nucleophosmin 1 (NPM1) mutations, correlating with worse survival rates, particularly in acute myeloid leukemia without CCAAT enhancer binding protein alpha (CEBPA) mutations." (PMID 40520993, 2025). "Recent preclinical studies on dual targeting of acute myeloid leukemia with a transgenic NPM1-antigen-specific TCR and a CD33 CAR revealed that double transgenic receptor expression led to better cytotoxicity and tumor control relative to single receptor-expressing T cells." (PMID 41181132, 2025). "Acute myeloid leukemia (AML) arises from the clonal expansion of aberrant hematopoietic stem cells, for which early events like CH-associated mutations together with later events like FLT3-ITD, NRAS or NPM1 mutations initiate the disease." (PMID 37880479, 2024). "In NPM1-mutated acute myeloid leukemia cells, HOXB-AS3 does not associate with polysomes and promotes cell proliferation in both human and mouse leukemia cells." (PMID 34280202, 2021). "Moreover, mutations in this area are responsible for the cytoplasmic mislocalization and malfunction of NPM1 during Acute Myelogenous Leukemia, showing that this small C‐terminal domain of NPM1 mediates important interactions." (PMID 34388291, 2021). "In addition, core binding factor acute myeloid leukemia (CBF-AML), nucleophosmin 1 (NPM1) and fms related receptor tyrosine kinase 3 (FLT3) in risk stratification have no impact on the expression of BRD4, PD-L1 and PD-1." (PMID 33658927, 2020). "The oncogenic role of NPM1 is mainly reported in acute myeloblastic leukemia (AML)." (PMID 32245950, 2020). "LncRNAs at the HOX gene locus are increased in expression in NPM1 mutant acute myeloid leukemia." (PMID 31767858, 2019). "Similarly, NPM1 stability is enhanced by interacting with erythroid differentiation-associated gene (EDAG), promoting acute myeloid leukemia (AML) cell survival." (PMID 27553022, 2016).
acute myeloid leukemia (continued). "This unclear role of NPM1 would change however, as it in 2005 was found that one-third of adult acute myeloid leukemia (AML) cases display aberrant cytoplasmic expression of NPM1 with mutations occurring in the exon-12 of NPM1, therefore directly implicating NPM1 as a cancer gene." (PMID 21152184, 2011). "In the same family, NPM1 has the ability to regulate the function of the tumour suppressor protein ARF, and is mutated in several haematological malignancies including 35% of acute myeloid leukaemias." (PMID 18840272, 2008). "Menin scaffolds the oncogenic histone-lysine-N-methyltransferase (KMT2A)-fusion protein (FP) complex in KMT2A-r and wild-type KMT2A complex in NPM1-m acute myeloid leukemia (AML)." (PMID 41959134, 2026). "The helical region spanning residues 264-277 represents a key amyloidogenic segment, and its conformational balance is involved in NPM1 misfolding in acute myeloid leukemia (AML)." (PMID 42222815, 2026). "The link between the nucleophosmin (NPM1) protein and the initiation of acute myeloid leukemia (AML) has been a long-term scientific project." (PMID 40647396, 2025). "Additionally, acute myeloid leukemia with NPM1 mutations (without FLT3–ITD) or in-frame CEBPA mutations in the basic leucine zipper region is now categorized as favorable-risk due to its heightened sensitivity to chemotherapy." (PMID 40362596, 2025). "Menin (MEN1) is a well-recognized powerful tumor promoter in acute leukemias (AL) with KMT2A rearrangements (KMT2Ar, also known as MLL) and mutant nucleophosmin 1 (NPM1m) acute myeloid leukemia (AML)." (PMID 39796769, 2025). "A 65-year-old woman was diagnosed with acute myeloid leukemia (AML-M2a subtype) on July 18, 2023,accompanied by mutations in FMS‐like tyrosine kinase 3 (FLT3)-ITD, NPM1, TET2, EZH2, and other genes." (PMID 39544304, 2024). "Moreover, the prognosis of relapse and/or refractory NPM1-mutated acute myeloid leukemias is not very encouraging, with median overall survival around 5–6 months." (PMID 39682203, 2024). "Rapid and accurate diagnosis of acute myeloid leukemia (AML) remains a significant challenge, particularly in the context of myelodysplastic syndrome (MDS) or MDS/myeloproliferative neoplasm with NPM1 mutations." (PMID 39390137, 2024). "Somatic mutations in genes such as NPM1, which is involved in the maintenance of HSCs’ quiescence and self-renewal, and TET2, DNMT3A, involved in mediating HSCs’ differentiation, results in the transformation of HSCs thereby leading to the development of Acute Myeloid Leukemia (AML)." (PMID 38571491, 2024). "Also groups of KAT6A- and NPM1-fusions are known in adult acute myeloid leukemia." (PMID 38086945, 2024). "Bimiralisib has also been shown to have efficacy in combination with BCL2 (B-cell lymphoma 2) inhibitor venetoclax in acute myeloid leukemia (AML) with IDH2, NPM1, and FLT3 mutations in preclinical studies." (PMID 38396649, 2024). "Among 113 CMML patients, 23(20.4%)were re-diagnosed as acute myeloid leukemia(AML), including 18 AML with NPM1 mutation, 3 AML with KMT2A rearrangement, and 2 AML with MECOM rearrangement." (PMID 37550186, 2023). "Along this line, INPP4B knockdown leads to a reduction in p-SGK3 levels, but did not influence AKT activation in NPM1-mutated OCI-AML3 acute myeloid leukemia cells and INPP4B expression is not correlated with alterations in AKT phosphorylation in leukemia, suggesting an AKT-independent mechanism." (PMID 36993823, 2023).
acute myeloid leukemia (continued). "In mixed-lineage leukemia (MLL), rearranged (MLLr+), or nucleophosmin 1 (NPM1)-mutated (NPM1c+) acute myeloid leukemia, HOTTIP expression is upregulated, which is associated with a poor survival rate in AML patients." (PMID 36983041, 2023). "Acute myeloid leukemia (AML) with mutated NPM1, a distinct diagnostic entity by the current WHO Classification of myeloid neoplasm, represents the most common diagnostic subtype in AML and is associated with a favorable prognosis." (PMID 35054502, 2022). "In this study, we aimed to investigate the impact of DNMT3A status on NPM1 MRD predictive value for survival in a retrospective cohort of acute myeloid leukemia (AML) patients aged over 60 years old treated intensively." (PMID 33947035, 2021). "Nucleophosmin (NPM1) mutations are considered as one of the most common genetic alteration in acute myeloid leukemia (AML), and aberrant cytoplasm-dislocated NPM1 mutant is a distinct biological characterization of this disease." (PMID 34769343, 2021). "For example, in acute myeloid leukemia (AML), an association between SNHG7 and SNHG12 lncRNAs and specific clinical/molecular features, including white blood cell (WBC) counts and mutations in IDH1, RUNX1, and NPM1 genes, shows high value of SNHG7 in correlation with extensive features." (PMID 35111760, 2021). "Oncogenic fusion proteins and gene mutations involving NPM1 have been described respectively in anaplastic large-cell lymphoma (ALCL) and acute myeloid leukemia (AML)." (PMID 34885010, 2021). "The cell-of-origin of NPM1- and FLT3-mutated acute myeloid leukemia (AML) is still a matter of debate." (PMID 31936647, 2020). "Herein we present a previously treated nucleophosmin (NPM1)-positive acute myeloid leukemia (AML) patient who later presented with isolated mediastinal MS." (PMID 30859798, 2019). "Recent studies identified a new cytomorphological feature in AML blasts and found a correlation of the so-called cup-like acute myeloid leukemia with mutations of FLT3 and NPM1." (PMID 31568521, 2019). "NPM1mA is a mutant form of the NPM1 gene and is the most common genetic abnormality in patients with acute myeloid leukemia (AML)." (PMID 30061177, 2018). "Few molecular markers have been used to predict treatment response and prognosis in cytogenetically normal acute myeloid leukemia (CN-AML), such as the nucleoplasmin (NPM1) gene and the fms-like tyrosine kinase 3 (FLT3) gene." (PMID 24667279, 2014). "Eligible patients included adults (≥ 18 years of age) with relapsed/refractory (R/R) acute myeloid leukemia (AML) or acute lymphoblastic leukemia (ALL) including but not restricted to those with KMT2A-rearrangement (r) or NPM1 mutation." (PMID 41310838, 2025). "Mutations in the nucleophosmin-1 (NPM1) gene and the internal tandem duplications (ITDs) of the fms-related tyrosine kinase 3 (FLT3) gene constitute two of the commonest mutations in Acute Myeloid Leukemia (AML), with a significant impact on prognosis." (PMID 40002262, 2025). "To elucidate the functional role of p-NPM1, we utilized a specific NPM1 inhibitor, NSC 348884, previously applied in acute myeloid leukemia (AML) models." (PMID 41145488, 2025).